INS (insulin)
Diseases named in the same sentence as INS in open-access papers (continued):
Sharing a sentence is not in itself a finding about the gene and the disease.
Hypoglycemia (continued). "Importantly, canonical autophagy is not involved in the degradation of insulin during hypoglycemia." (PMID 38132137, 2023). "To date, the relationship between fasting and insulin-induced hypoglycemia has not been well characterized, so our objective was to determine whether insulin-independent factors, such as counterregulatory hormone responses, are adversely impacted by fasting in healthy control individuals." (PMID 37166980, 2023). "Finally, the same report indicated that the use of U-500 regular insulin “both as MDI and via CSII was not reported to be associated with severe hypoglycemia but was associated with an increase in patient satisfaction as well as in cost savings”, which is in agreement with our clinical experience." (PMID 36676765, 2023). "Based on our daily clinical practice, all of these factors, either individually or collectively, may contribute to non-adherence and insulin discontinuation, with hypoglycemia often cited by patients as a major reason for discontinuing insulin or diverting from the prescribed insulin regimen." (PMID 38047210, 2023). "In conclusion, we found that the implementation of an SQ insulin-driven protocol for treating DKA was associated with substantial changes in practice, including a significantly decreased need for intensive care and reduced rates of readmission, with no increase in hypoglycemia or mortality." (PMID 35389497, 2022). "Moreover, individuals with high serum Ca may obscure the symptoms of hypoglycemia by producing less insulin during fasting than those with normal serum Ca; hence, they should be more alert to the occurrence of HH." (PMID 35698198, 2022). "A recent meta-analysis has not shown an increased risk of hypoglycaemia with the administration of SGLT2 inhibitors alone, and this is in accordance with the mechanism of action of these drugs that are not able to increase the release of insulin or influence the glucose synthesis." (PMID 36211584, 2022). "No dextrose:insulin ratio used in this population predictably prevented the development of hypoglycemia; however, this study showed that a dextrose:insulin ratio of 2 g/u is inadequate in preventing hypoglycemia in some cats, regardless of whether a dextrose-containing CRI is administered." (PMID 36350735, 2022). "However, this patient was not an insulin user, had no comorbidities or history of SH, exercised regularly for her health, and had a sufficiently high fasting glucose level (7.7 mmol/L) to not consider nocturnal hypoglycemia." (PMID 36246915, 2022). "Compared to those who did not suffer from severe hypoglycemia, patients with severe hypoglycemia at baseline had higher prescriptions of various anti-glucose drugs, including sulfonylurea, meglitinide, thiazolidinedione, alpha-glucosidase inhibitor, and insulin." (PMID 33678721, 2022). "Furthermore, there was no match with regard to hypoglycemia rates prior to insulin initiation and there was an imbalance that could per se drive the differences of the changes in hypoglycemia rates with Deg-100 versus Glar-300." (PMID 35864262, 2022). "Our patient did not experience any hypoglycemia symptoms while she was on insulin therapy during pregnancy because she had been on a relatively low dose of insulin (the maximum dose received was 9 units of basal insulin and 6 units of mealtime insulin) all along." (PMID 36483860, 2022). "However, this hypothesis cannot explain the spontaneous and intermittent hypoglycaemia symptoms in our patient who had no endogenous insulin production and did not receive exogenous insulin during the monitoring." (PMID 36440205, 2022). "From a pharmacological point of view, it would be relevant to examine whether or not treatment with α5IA or S44819 would reverse the insulin-induced reprogramming of the counter-regulatory response to hypoglycemia or even prevent it from developing in the first place." (PMID 35207609, 2022).
Hypoglycemia (continued). "Also, it was noted that hypoglycaemia had not repeated after insulin dose adjustment." (PMID 36326405, 2022). "Other studies in adults showed that the post-prandial spike is more effectively controlled by proper timing of insulin administration rather than increasing the pre-meal insulin dose or administering a super-sized correction bolus, which could result in hypoglycemia." (PMID 36556278, 2022). "While no specific dextrose:insulin ratio was found to protect against hypoglycemia, there is evidence that the commonly recommended dextrose:insulin ratio of 2 g/u may be inadequate in preventing hypoglycemia in every cat." (PMID 36350735, 2022). "However, in systematic reviews, one study reported less episodes of hypoglycaemia when salbutamol nebulisations were added to insulin therapy, and another reported no episodes when variable combinations of salbutamol and sodium bicarbonate were added to insulin." (PMID 35552566, 2022). "SGLT-2Is and dipeptidyl peptidase-4 inhibitors (DPP-4Is) do not cause hypoglycemia, are administered orally (The Royal Australian College of General Practitioners (RACGP), 2016), and may be preferred over sulfonylureas and insulin in people at high risk of hypoglycemia such as those who are frail." (PMID 35903329, 2022). "It was shown that radish sprout consumption decreased plasma levels of fructosamine, glucose, and insulin, suggesting that the hypoglycemia brought on by radish sprout consumption may not be related to an increase in insulin synthesis but rather to enhanced sensitivity or an insulin-like action." (PMID 36364145, 2022). "For instance, therapies that could achieve ghrelin cell–selective IR blockade would presumably help protect against insulin-induced hypoglycemia (by preventing insulin-induced drops in ghrelin) without gains in body weight, which are often considered unwelcome." (PMID 34473648, 2021). "However, although this effect has been ascribed in the past to preserved insulin secretion, no studies, to our knowledge, have examined the impact of C-peptide per se on glucagon secretion in response to insulin-induced hypoglycemia." (PMID 34003799, 2021). "Interestingly, the promotion of insulin secretion did not occur under hypoglycemia after fasting." (PMID 33804798, 2021). "Furthermore, FBG ≥ 7 mmol/L and fasting insulin ≥ 9.30 mu/L are protective factors for hypoglycemia, which has not been reported in other studies and may be because of the specificity of intensive insulin therapy." (PMID 33015194, 2020). "In addition, insulin-induced hypoglycemia increases ARC POMC neuron activity, supporting the interpretation that ARC POMC neurons may play a critical role in the counterregulatory response to hypoglycemia." (PMID 33293550, 2020). "In addition, the decrease in insulin may be due to the response to hypoglycemia, which does not rule out the possibility of abnormal pancreatic function, although the damage of pancreas was not visible by histology examination." (PMID 33236987, 2020). "For low-to-moderate-intensity aerobic activities lasting 30–60 min that are undertaken when circulating insulin is at basal levels, the intake of small amounts (8–20 g) of carbohydrate may suffice to limit hypoglycaemia, but are not likely to affect performance." (PMID 32533229, 2020). "In addition, impaired α cells severely limits the ability to regulate treatment related hypoglycemia, which used to be considered a minor problem in T2DM, but is now thought to be underestimated and drawing more attentions due to elevated usage of insulin treatment." (PMID 33250773, 2020). "A third caveat relates to the use of ghrelin-KO mice, which, because of long-term absence of ghrelin, could exhibit a phenotype reflective of potential compensatory developmental changes that alter the true effects of absent ghrelin action in the setting of insulin-induced hypoglycemia." (PMID 33042003, 2020).
Hypoglycemia (continued). "Using insulin may be dangerous without appropriate vigilance as it can lead to severe hypoglycemia." (PMID 30840630, 2019). "Furthermore they may be taking only metformin, unlikely to be on insulin or sulphonylyureas, and may have lesser microvascular complications, so they are less prone to hypoglycemia." (PMID 30819208, 2019). "However, accurate administration of insulin to maintain normoglycaemia is difficult; too little will not regulate glucose and too much exogenous insulin may produce hypoglycaemia." (PMID 30635569, 2019). "However, in adults, under hyperinsulinemic conditions, the rate of fall in blood glucose levels may result in hypoglycemia if prolonged exercise is initiated within this starting range, without any adjustment to insulin dose or carbohydrate intake." (PMID 31258513, 2019). "Other experimental studies using rat islet cells also suggest that fluoroquinolones act not as initiators but as augmenters of stimulated insulin release from these cells, which might be a reason that the majority of the episodes of hypoglycemia in our patient were occurring postprandially." (PMID 31078137, 2019). "Although it is not obvious whether TH and/or treatment including insulin and glucose-free fluid cause hypoglycemia, it seems clear that the EAG group had a higher risk for the development of hypoglycemia since it had a lower mean glucose level than the standard group." (PMID 31540352, 2019). "This supports the clinical observations that large doses of insulin may be needed to achieve pregnancy glucose targets in women with GCK-MODY and those who reach pregnancy glucose targets frequently report autonomic symptoms of hypoglycemia [personal communications ATH & MH Shepherd]." (PMID 30146176, 2018). "However, the severe hypoglycemia phenotype may be not triggered by the abnormal insulin level, because blood insulin levels are even lower than in wild-type mice." (PMID 29535637, 2018). "Moreover, no hypoglycemia-related events occurred in these patients, which might due to the absence of preprandial insulin and insulin-stimulating drugs." (PMID 30302121, 2018). "Thus, our data suggest that the main physician expectations with regard to switching persons with T2DM to basal insulin analogues—achieving good glycemic control without hypoglycemia or weight gain—can indeed be met in routine clinical practice, outside the clinical trial setting." (PMID 29460260, 2018). "However, a recent meta-analysis that found intraoperative insulin therapy may not increase the rate of hypoglycemia." (PMID 29929558, 2018). "Moreover, although hypoglycaemia does not occur with these agents per se, they may increase hypoglycaemia when combined with a sulfonylurea or insulin." (PMID 29777264, 2018). "Furthermore, because basal insulin was not titrated to target and because the placebo arm had no active intervention, the comparison of hypoglycemia rates between the arms and the applicability of the study findings to clinical practice should be interpreted according to these limitations." (PMID 29688502, 2018). "The glycaemic thresholds for symptoms of hypoglycaemia and for glucose counterregulatory (including sympathoadrenal) responses to hypoglycaemia, as plasma glucose concentrations fall, are not fixed in patients with insulin-, sulfonylurea- or meglitinide- (glinide)-treated diabetes." (PMID 27872948, 2017). "In a randomized controlled trial of a mixed critically ill patient population, the use of the LOGIC-Insulin blood glucose control algorithm, compared with blood glucose control by expert nurses, improved the quality of blood glucose control without increasing hypoglycemia." (PMID 28806982, 2017). "The lack of newly diagnosed/treated patients (<12 months insulin use) in HAT could affect the observed rates of hypoglycaemia; however, this group is only a small proportion of the total population with T2DM and is unlikely to have a significant effect on the mean values." (PMID 27161418, 2016).
Hypoglycemia (continued). "Similarly, assistance from family members at the time of insulin injection [presence/absence, OR (95% CI): 0.19 (0.05–0.75)] and those on intensive insulin therapy [yes/no, OR (95% CI): 3.61 (1.06–12.26)] affected severe hypoglycemia." (PMID 26102197, 2015). "In the past decade, studies of the effects of insulin in the brain have been enhanced after development of non-invasive methods of selective delivery of insulin into the brain, via the intranasal route, circumventing peripheral effects of systemic hypoglycemia." (PMID 25705204, 2015). "The lack of feeding, the use of intensive insulin therapy prior to the publication of the 2010 guidelines, and increased insulin sensitivity during rewarming may have influenced the high incidence of post-rewarming hypoglycemia within 72 hours after ROSC." (PMID 26202789, 2015). "In addition, for insulin-dependent diabetics, this work schedule leads to changes in meal times and consequently in timing of insulin doses, which needs to be changed without inducing episodes of hypoglycemia." (PMID 25892993, 2015). "Although the ICU nurses were not allowed to change insulin infusion rates, they could have anticipated hypoglycemia by performing new blood glucose measurements earlier than dictated by the local guideline for blood glucose control, allowing them to respond earlier to, for example, hypoglycemia." (PMID 25652770, 2015). "Thus, it is plausible that the long-acting insulin may not have elevated fasting glucose levels, but have elevated glucose levels immediately after breakfast in response to nocturnal asymptomatic hypoglycemia." (PMID 26625003, 2015). "In conclusion, despite the limitations of a single case report, the clinical history described suggests that disease progression and increasing levels of serum insulin may not be considered the only criterion for discontinuing everolimus therapy whenever hypoglycemia is controlled." (PMID 25298880, 2014). "This substantial stability of the nanocoating layers may be important for more predictable release of insulin (with the absence of unpredictable hypoglycemia) after oral administration than was the case with the insulin-chitosan alone, which we demonstrated in this study." (PMID 24833901, 2014). "In addition, those taking insulin were not at increased risk of PAD, indicating the increased risk of PAD in those on glibenclamide may not be related to the known risk of hypoglycemia that occurs with glibenclamide." (PMID 24913468, 2014). "It had been reported that liraglutide could dose-independently enhance glucose-dependent insulin secretion without causing hypoglycemia, which indicated an insulin-like effect on T2DM, decreased postprandial glucose levels, improved glycemic control, and lowered insulin dose in patients with T2DM." (PMID 25183970, 2014). "Furthermore, a fourth episode of insulin-hypoglycemia failed to increase VMH ROS production." (PMID 23894333, 2013). "However, we did not observe increased cortical NO release following insulin-hypoglycemia." (PMID 23894333, 2013). "Patients in the insulin-increasing group experienced similar glucose control compared with that in the liraglutide-added group, but when compared with the composite endpoint including HbA1c ≤ 7.0% with no weight gain and no hypoglycemia, there is a significant difference between two groups." (PMID 23153177, 2012). "A positive correlation was demonstrated in the following variables: “My clinic/hospital is not equipped to provide insulin therapy” (β = 0.334), “If necessary, I can refer the patients to a specialist” (β = 0.230), and “My clinic/hospital is unable to provide treatment for hypoglycemia” (β = 0.191)." (PMID 22719830, 2012). "However, responses to insulin-induced hypoglycemia have not been tested." (PMID 22969729, 2012).
Hypoglycemia (continued). "Once the Sik3−/− mice were supplied exogenously with an energy source, such as lactate (lactate tolerance test), they were able to produce glucose efficiently, suggesting that the hypoglycemia of Sik3−/− mice may be due to a lack of energy storage followed by an enhanced insulin response." (PMID 22662228, 2012). "However, only one small retrospective study had shown that adding liraglutide to insulin therapy resulted in a significant improvement in glycemic control, reduction in insulin requirement, and reduction of body weight without significant hypoglycemia." (PMID 23153177, 2012). "In my experience, most hypoglycemia is not due to these simple dosing errors; rather it is due to the complexity of selecting the optimal dose and type of insulin in patients whose insulin requirements are unknown and whose severity of illness and carbohydrate intake is fluctuating." (PMID 23882328, 2011). "Another plausible explanation for the low rate of hypoglycaemia is that some patients may not have received adequate titration of their insulin dose by their primary care physicians in accordance with recommended levels, as indicated by the modest reduction in HbA1c levels observed in the study." (PMID 20946269, 2010). "The drug showed optimum activity at 250 mg/kg and further increase in extract dose did not result in a further significant decline in blood glucose levels, thus it appears that unlike insulin and other common hypoglycaemic agents overdose of the drug may not result in hypoglycemia." (PMID 19943967, 2009). "Considering the lag time between effective insulin titration and resulting improvement in HbA1c, the most plausible explanation for the lower HbA1c observed with detemir at the end of trial is that it can be titrated more aggressively than NPH without unacceptable risk of hypoglycaemia." (PMID 18387078, 2008). "Funnel plots did not suggest the presence of publication bias for HbA1c, BW, hypoglycaemia level 3, TIR, TAR, total insulin dose and bolus insulin dose." (PMID 41048193, 2026). "The incidence of physical activity-attributed clinically significant or severe hypoglycaemia was generally low in ONWARDS 1–5 and was not statistically significantly different between icodec and once-daily insulin comparators." (PMID 40186685, 2025). "Unlike insulin-mediated hypoglycemia, IGF-2-induced hypoglycemia is characterized by low insulin, low C-peptide, low β-hydroxybutyrate, and variable cortisol levels." (PMID 41333493, 2025). "Insulin therapy is the standard of care in patients with T1DM at the expense of increasing weight, hypoglycemia, and lack of cardiovascular protection." (PMID 40852189, 2025). "As such, a diagnosis of nesidioblastosis can be made from the history of hyperinsulinemic post-prandial hypoglycemia, lack of pancreatic mass on cross-sectional imaging, and SACST showing a diffuse pattern of insulin release." (PMID 40395710, 2025). "A crossover RCT involving 20 adults with CFRD showed glycemic outcomes were improved using the insulin-only iLet Bionic Pancreas compared to usual care (TIR: 75% vs 62%), with no increase in hypoglycemia." (PMID 39390689, 2024). "Spontaneous hypoglycemia in the absence of insulin therapy following TPIAT is a recognized complication, which has been attributed to lack of protective glucagon responses to hypoglycemia, following intrahepatic islet autotransplantation." (PMID 39450137, 2024). "The current study revealed that incorporating long-acting insulin into the standard treatment protocol for DKA did not lead to an increase in side effects, such as cerebral edema, hypokalemia, or severe hypoglycemia." (PMID 40433420, 2024). "DPP-4 inhibitors have advantages such as lack of hypoglycaemia and weight gain which justifies combining DPP-4 inhibitors with insulin." (PMID 37287751, 2023). "Fasting is known to increase hepatic insulin sensitivity, although this would not be expected to suppress HGP during hypoglycemia." (PMID 37166980, 2023).